HIF1A (hypoxia inducible factor 1 subunit alpha)
Diseases named in the same sentence as HIF1A in open-access papers (continued):
Sharing a sentence is not in itself a finding about the gene and the disease.
bone tumor (12 papers, 2016 to 2025). "Recently, several studies have shown the association of HIF-1α expression with the outcome of bone tumors." (PMID 35893766, 2022). "Although we evaluated comprehensively the association between HIF-1α and bone tumor outcome, there were several limitations in this meta-analysis." (PMID 30782196, 2019). "Furthermore, high HIF-1α expression is strongly associated with the microvessel density of bone tumors." (PMID 35893766, 2022). "The potential for HIF-1α to become a prognostic marker was further strengthened by a meta-analysis on bone tumors that revealed a significant correlation between the overexpression of HIF-1α and overall/disease-free survival." (PMID 38534356, 2024). "Association studies between HIF-1α, its downstream targets and prognosis in patients with bone tumors have shown unfavorable overall survival in patients with a high expression of HIF-1α." (PMID 35893766, 2022). "The pooled results showed that HIF-1α overexpression was significantly associated with poorer OS and shorter DFS in patients with bone tumor." (PMID 30782196, 2019). "PubMed, Cochrane Library, Web of Science, China National Knowledge Internet, and Wanfang databases were used to search the relationship between HIF-1α and bone tumor." (PMID 30782196, 2019). "It is necessary to carry out a meta-analysis of all the current available data to clarify the relationship between HIF-1α and survival or clinicopathological features of bone tumor." (PMID 30782196, 2019). "In order to clarify the effect of HIF-1α on the clinicopathological and prognostic value in the bone tumor, a meta-analysis was performed to systematically evaluate the relationship between HIF-1α expression and bone tumor." (PMID 30782196, 2019). "What was more, HIF-1α overexpression was also significantly associated with the differentiation, clinical stage, metastasis, and MVD of bone tumor." (PMID 30782196, 2019). "Articles investigating clinicopathological and prognostic value of HIF-1α in bone tumor patients were enrolled in this meta-analysis." (PMID 30782196, 2019). "Out of the 28 studies, 22 studies evaluated the relationship between HIF-1α expression and the clinicopathological features of bone tumor, and 14 studies reported survival data." (PMID 30782196, 2019). "The pooled risk ratios (RRs) and hazard ratios (HRs) were used to evaluate the clinicopathological and prognostic value of HIF-1α on bone tumor patients, respectively." (PMID 30782196, 2019). "The 2ΔΔCt values of HIF-1α and FoxO1 were significantly increased in bone cancer tissues relative to normal adjacent tissues (p < 0.05)." (PMID 31905813, 2019). "Recently, many studies have shown the role of hypoxia-inducible factor-1α (HIF-1α) expression in the outcome of bone tumor." (PMID 30782196, 2019). "A total of 888 studies were retrieved on initial literature search that related to the clinicopathological and prognostic value of HIF-1α in patients with bone tumor." (PMID 30782196, 2019). "The immunocytochemistry assay results showed that HIF-1α and FoxO1 protein expression was significantly increased in bone cancer tissues compared with normal adjacent tissues." (PMID 31905813, 2019). "Furthermore, the hypoxic microenvironment in the bone tumour microenvironment (TME) involves HIF-1α and CXCR4 pathways." (PMID 41315643, 2025). "Altogether, these findings suggest that the clearance of apoptotic cancer cells by BM macrophages triggers p-STAT3/HIF-1α/MIF signaling to promote further inflammation in the bone tumor microenvironment where a significant number of apoptotic cancer cells are present." (PMID 36496973, 2022). "However, the clinicopathological and prognostic value of HIF-1α has been controversial in patients with bone tumor." (PMID 30782196, 2019).
bone tumor (continued). "In addition, this study also analyzed the role of HIF-1α expression in clinicopathological features, which were closely related with the severity of bone tumor, including differentiation, clinical stage, metastasis, and microvessel density." (PMID 30782196, 2019). "The relation between HIF-1α overexpression and the OS of patients with bone tumor was also present in studies with less than 100 months (HR = 2.55, 95% CI 1.97–3.30, P < 0.001) as well as more than or equal 100 months follow-up time (HR = 2.76, 95% CI 1.88–4.04, P < 0.001)." (PMID 30782196, 2019). "Our results showed that high expression levels of HIF-1α were associated with poorer OS (overall survival) (HR = 2.61, 95% CI 2.11–3.23, P < 0.001) and shorter DFS (disease-free survival) (HR = 2.02, 95% CI 1.41–2.89, P < 0.001) in bone tumor." (PMID 30782196, 2019). "Furthermore, HIF-1α plays an important role in the bone tumor involved in pivotal aspects of tumor biology." (PMID 30782196, 2019). "In addition, HIF-1α can also play a significant role in bone tumor." (PMID 30782196, 2019). "Furthermore, we performed multiplex IHC staining in those bone tumors and found that pro-tumoral TAMs (F4/80+CD206+) were significantly reduced in ASH1L-expressing tumors upon HIF-1α inhibitor treatment." (PMID 40394007, 2025). "Similar findings were also presented by a research on bone-cancer induced pain (BCP), showing that downregulation of ANXA3 using shRNA substantially inhibited the expression of HIF1α and VEGF in the ipsilateral spinal cord and microglial cells of mice undertaken 21 days of bone cancer induction." (PMID 34355022, 2021). "HIF-1α overexpression indicated an unfavorable factor for OS and DFS in bone tumor, suggesting that HIF-1α may serve as a potential prognostic marker for bone tumor." (PMID 30782196, 2019). "High expression level of HIF-1α significantly predicted unfavorable OS in bone tumor (HR = 2.61, 95% CI 2.11–3.23, P < 0.001), without any heterogeneity in the data (fixed effects model: χ2 = 5.70, I2 = 0, P = 0.770)." (PMID 30782196, 2019). "Both target genes were significantly upregulated in bone tumors from mice on HFD as compared to LFD mice, a result that complemented a significant increase in the levels of GLUT1, another direct target of HIF-1α activity." (PMID 27588494, 2016). "Furthermore, we investigated the relationship between HIF-1α expression and DFS of bone tumor." (PMID 30782196, 2019).
brain cancer (12 papers, 2011 to 2025). A primary or metastatic malignant neoplasm affecting the brain. "Significant associations between HIF-1α overexpression and patient mortality have been shown in cancers of the brain, breast, cervix, oropharynx, ovary, and uterus." (PMID 21843314, 2011). "Carbonic anhydrase-IX (CA-IX), a marker overexpressed during HIF-1α transcription under hypoxia in brain tumors, plays a crucial role in malignant brain tumor therapy via the downstream inhibition of HIF-1." (PMID 39459028, 2024). "The cell viabilities of NSCLC, breast, gastric, and brain cancer cells were decreased more by HIF-1α than in the case of HIF-2α knock down." (PMID 32847073, 2020). "In vitro, ACF induced apoptosis and interfered with HIF-1α survival pathways in several brain cancer cell lines." (PMID 29097800, 2017). "Our findings introduce locally delivered ACF as an effective and promising therapeutic option and show that HIF-1α-targeting molecular therapy has the potential to mark a new step forward in the treatment of brain cancer." (PMID 29097800, 2017). "Here we describe the efficacy of a HIF-1α inhibitor, Acriflavine, and demonstrate its potency against brain cancer." (PMID 29097800, 2017). "However, cell proliferation of NSCLC, breast, gastric, and brain cancer cells under hypoxia was more dependent on HIF-1α except for HCC cells where it was more dependent on HIF-2α." (PMID 32847073, 2020). "The reciprocal interaction between TLRs and HIF-1α suggests that hypoxia-induced TLR9 expression may also be HIF-1α-regulated in brain cancer cells." (PMID 24959259, 2014). "In prostate, liver and brain cancer cell lines, ID1 was inhibited in hypoxia in HIF1α-expressing controls, but was consistently reinstated in HIF1α-KD cells." (PMID 34820369, 2021). "Most available studies on solid tumors, including breast, cervical, and brain cancer studies, have shown significant overexpression of the HIF-1α protein regardless of oxygenation of the tumor tissue and its adverse prognostic effect on the RT used." (PMID 37296922, 2023).
Cirrhosis (12 papers, 2013 to 2025). A chronic disorder of the liver in which liver tissue becomes scarred and is partially replaced by regenerative nodules and fibrotic tissue resulting in loss of liver function. "Cirrhosis causes hypoxia in liver cells, inducing the expression of HIF-1α in host cells and increasing the level of DNase I in the host." (PMID 41156629, 2025). "Hepatic cirrhosis, for instance, is associated with hypoxic microenvironments due to impaired hepatic oxygen delivery and vascular remodeling, leading to increased HIF-1α activation." (PMID 40004007, 2025). "HIF-1α expression was correlated to poor prognosis of HCC patients with cirrhosis and high HIF-1α and Sp1 co-expression were also found to be associated with poorer prognosis of HCC patients." (PMID 36139684, 2022). "HBV-induced cirrhosis leads to a hypoxic environment in hepatocytes, which induces the expression of the hypoxia-inducible factor HIF-1α." (PMID 41156629, 2025). "In conclusion, YGJ and iYGJ had anti-angiogenic effects in a CCl4-induced cirrhosis mouse model and how this occurred is likely through improvement of hepatic hypoxia and inhibition of the HIF-1α/VEGF signaling pathway." (PMID 26427787, 2015). "miR-155 and -199, while not observed in our studies, were implicated in studies of rat liver cells and endothelial cells in humans in response to chronic alcohol insult, and lead to inflammation in cirrhosis through endothelin-1 (ET-1) and hypoxia-inducible factor-1α (HIF-1α)." (PMID 35126468, 2021). "In addition, HIF-1α expression profile was also correlated with severity of cirrhosis (P < 0.05)." (PMID 23496980, 2013). "Collagen I, α-smooth muscle actin (α-SMA), HIF-1α, and CAT expression of normal and cirrhosis tissues were then subjected to immunofluorescence staining." (PMID 36797395, 2023).
fungal infections (12 papers, 2007 to 2025). "We demonstrate that the transcription factor HIF-1α is crucial to orchestrate a proper immune response in this model and control fungal infection by regulating neutrophil recruitment and survival through the chemokine CXCL1." (PMID 36275017, 2022). "This indicates that HIF-1α is crucial for the response not only to both invasive and chronic fungal infection but implicates likely overlapping regulatory mechanisms." (PMID 36275017, 2022). "HIF-1α is an important mammalian regulator of gene expression during hypoxia, but also plays a key role in the regulation of host immune responses during fungal infections." (PMID 32977563, 2020). "During this review, we will focus on a comprehensive overview of the role of autophagy and HIF-1α on the outcome of fungal infections." (PMID 32977563, 2020). "HIF-1α inhibition increased TNF and IL-10 levels after Candida infection, and it has been previously shown that HIF-1α controls progression of fungal infections by limiting IL-10 production." (PMID 32999407, 2020). "Recent research confirmed that the HIF-1α-dependent glycolytic pathway is essential for the macrophage functional differentiation in protecting against bacterial and fungal infections." (PMID 31182997, 2019). "In this study, we investigated and compared the roles of HIF1α in different macrophage functional effects of bacterial and fungal infections in vitro and in vivo." (PMID 29483608, 2018). "In the present study, we further showed that HIF1α-dependent glycolytic pathway is essential for the macrophage functional differentiation in protecting against bacterial and fungal infections in vitro and in vivo." (PMID 29483608, 2018). "Together, these data showed that HIF1α is required for macrophage differentiation during fungal infection." (PMID 29483608, 2018). "Furthermore, under normoxic conditions LPS induces HIF-1α expression via MyD88/NFκB signaling in macrophages, and mice deficient in HIF-1α are more susceptible to a variety of bacterial and fungal infections." (PMID 40191198, 2025). "A recent study demonstrated that hypoxia-inducible factor-1α (HIF-1α), a metabolic regulator, promotes macrophage glycolysis metabolism, resulting in proinflammatory macrophage functional differentiation and protection against bacterial and fungal infections." (PMID 35638785, 2022). "Hif-1α stabilisation has potential as a HDT for treatment of fungal infections but requires appropriate in vitro models that allow both genotypic and phenotypic characterisation of the effects of Hif-1α stabilisation on fungal infection and immune cell behaviour." (PMID 36012793, 2022). "This study also contributes to the body of knowledge on HIF-1A in fungal infections and suggests it might also be important for proper inflammatory response during PCP." (PMID 34066663, 2021). "Thus, the HIF1α-dependent glycolytic pathway is essential for pro-inflammatory macrophage functional differentiation in protecting against bacterial and fungal infections." (PMID 29483608, 2018). "Thus, combined with the experimental results in vivo and in vitro, the HIF1α-dependent glycolytic pathway is essential for the macrophage functional differentiation in protecting against bacterial and fungal infections." (PMID 29483608, 2018). "Here, we showed that C. albicans can cause significant pro-inflammatory macrophage polarization and that HIF1α-glycolytic pathway mechanisms are required for the mediation of pro-inflammatory macrophage polarization in protecting against C. albicans fungal infection in vivo and in vitro." (PMID 29483608, 2018). "Additionally, this work supports the strategy of exploring HIF1α as a therapeutic target in specific immunosuppressed populations with fungal infections." (PMID 25255025, 2014).
fungal infections (continued). "Proof of principle for the potential of such intervention is shown by amphotericin B, a commonly used treatment for systemic mycoses, which enhances the interaction between HIF-1α C-terminal TAD and FIH-1, thereby blocking p300 recruitment and suppressing hypoxia-induced erythropoietin production." (PMID 18096060, 2007). "Neutrophil viability was significantly reduced in the absence of HIF-1α upon fungal challenge, suggesting an inability of mHif1α-/- neutrophils to cope with fungal infection." (PMID 36275017, 2022).
Lewis lung carcinoma (12 papers, 2016 to 2025). "We investigated the combined effects of Kanglaite (KLT) and cisplatin on tumor associated macrophage (TAM) and expression of hypoxia inducible factor-1 alpha (HIF-1α) in Kunming mice with Lewis lung carcinoma." (PMID 30087869, 2018). "In a Lewis lung carcinoma model, polarization of tumor associated macrophages towards an M2-like phenotype was dependent on HIF-1α induced by tumor-derived lactic acid, a by-product of glycolysis." (PMID 28892492, 2017). "Furthermore, decreases in VEGF and hypoxia-inducible factor 1α (HIF-1α), a major transcription factor implicated in tumor neovascularization, were found to be associated with a cisplatin-induced reduction in vessel density in a Lewis lung carcinoma model." (PMID 30344920, 2018). "More interestingly, FK228, a specific histone deacetylase (HDAC) inhibitor, has been reported to decrease hypoxia‐induced angiogenesis by suppression of HIF‐1α activity in Lewis lung carcinoma model." (PMID 33377619, 2021). "In this study, we found for the first time that Pvt1 is a target of HIF-1α under hypoxia in G-MDSCs from Lewis lung carcinoma mice." (PMID 30925926, 2019). "To determine the effects of HIF-1α methylation on tumour angiogenesis and progression, we employed a Lewis lung carcinoma (LLC) tumour model by subcutaneously implanting LLC tumour cells into the flanks of WT and Hif1aKA/KA mice." (PMID 26757928, 2016). "A Lewis lung carcinoma (LLC) mouse model was established to assess the in vivo function of PDLIM2 and HIF-1α." (PMID 38880883, 2024). "The combined treatment of DHA-DDF and ultrasound could induce apoptosis, inhibit the migration and invasion of Lewis lung carcinoma (LLC) cells, and down-regulate the expression of HIF-1α and VEGF in LLC cells." (PMID 40852643, 2025).